TNF (tumor necrosis factor)
Diseases named in the same sentence as TNF in open-access papers (continued):
Sharing a sentence is not in itself a finding about the gene and the disease.
infection (continued). "Cell death was induced by TNF-α (100 ng/mL; 12 h), followed by subsequent infection with E. chaffeensis." (PMID 37594275, 2023). "ELISA results showed decreased levels of inflammatory cytokines IL-6, IL-1β, and TNF-α at each infection time point." (PMID 38076459, 2023). "Infection with NTHi is also associated with transcriptional upregulation of cytokines CCL2 (MCP1), TNF, IL-1β, IL-6, CXCL8 and alarmins (TSLP, IL-33 and IL-25)." (PMID 37180449, 2023). "Not only cellular infection of SARS-CoV-2 but also inflammatory mediators, including TNF-α and IFN-γ, can cause programmed necrosis." (PMID 36507222, 2023). "As a result, when the IL-10/TNFα ratio is elevated, it leads to the recruitment of a higher number of macrophages and neutrophils that produce IL-10 at the infection site." (PMID 38196634, 2023). "Leukocytes play a fundamental role in the healing of injuries due to the anti-infection action and immunological regulation through the secretion of immune cytokines, such as interleukin (IL)-1β, IL-4 and IL-6, and tumor necrosis factor alpha (TNF-α)." (PMID 37330965, 2023). "In mammals, alveolar macrophages exhibited polarization toward the M1 phenotype 4 h after H9N2 AIV infection, with the upregulation of M1-associated marker genes STAT1, TNF-α, MCP1, INOS, IL-6, and IL-12." (PMID 37357919, 2023). "In contrast, low-infected larvae show lower TNFα and IL1β responses and were able to control parasitaemia and recover from the infection." (PMID 36829432, 2023). "This reduction was accompanied by a diminished immune response to infection, as indicated by the lowered levels of TNF-α, IL-6, and IL-10 and altered CD4+/CD8+ T-cell ratio." (PMID 38139181, 2023). "Del2R infection significantly increased the expression of IL-1β and TNF-α mRNA by approximately 20-fold at 12 and 20 hpi, compared with ASFV-WT." (PMID 37566637, 2023). "TNF-α, a cytokine that is increased during infection, does reduce parasite numbers in infected epithelial cells in vitro through limiting invasion of host cells." (PMID 37325809, 2023). "Inflammatory cytokines TNF-α and IL-6 are swiftly and transiently produced in response to infection and tissue injury." (PMID 38138520, 2023). "The adjuvant group had a better effect in reducing TNF-α and IL-6 expression, which provided a basis for survival protection after infection in mice compared with the HA group." (PMID 37868069, 2023). "CRP acts as an acute phase plasma protein in response to inflammation or infection; it is regulated by proinflammatory cytokine stimulation such as tumor necrosis factor-alpha, interleukin-1 (IL-1), and IL-6." (PMID 36674837, 2023). "In general, infection and disease induce fever, a physiological defensive response mediated by cytokines, such as TNF-α, IL-1β, and IL-6." (PMID 37621534, 2023). "Regarding the inflammatory cytokines, including G-CSF, GM-CSF, TNF-α, IL-1b, IL-6, and IL-17, the HD patients in the breakthrough infection group had higher TNF-α and IL-6 levels than those in the booster immunization group (p = 0.017 and 0.039, respectively)." (PMID 37515030, 2023). "The hepatitis E virus can cross the BBB in a TNF-α independent fashion and produce a productive infection in brain endothelial cells, increasing brain TNF-α and interleukin 18 (IL-18) levels that are associated with perivascular inflammation and gliosis." (PMID 36768699, 2023). "This strain was shown to protect zebrafish larvae against V. anguillarum PF4 infection by preventing the expression of inflammatory cytokines IL1β and TNFα." (PMID 36836388, 2023). "After infection, the RNA level of IL-1β (p = 0.004) and TNF-α (p = 0.001) increased compared to controls, and these were significantly and dose-dependently inhibited (p < 0.05) by zingerone." (PMID 37626627, 2023).
infection (continued). "We analyzed hLO culture supernatants for the presence of ten cytokines and chemokines commonly produced by epithelial cells in response to infection (TNF-α, IFN-α2a, IFN-β, IFN-λ1, IL-8, IL-1α, IL-1β, IL-6, IP-10, MCP-1)." (PMID 37883246, 2023). "Cases of penetrating infections led to considerably higher antibody levels in IBD patients under anti-TNF therapy compared to uninfected patients." (PMID 37766088, 2023). "TNF was able to inhibit C. burnetii intracellular replication when added as late as 3 days post-infection, and C. burnetii was able to replicate within macrophages following the removal of rTNF treatment at 24 hours post-infection." (PMID 37461589, 2023). "Curiously, the pyrin domain of C1 alone enhanced cellular responses to TNFα, which potentially implicates the Bcl-2 domain for a role in preventing aberrant activation of cellular inflammatory pathways by C1 during infection." (PMID 36909515, 2023). "Nisin treatment also significantly reduced the expression of TNF-α mRNA in the infected group compared to the infection group." (PMID 37803465, 2023). "The activated macrophages polarized into the M1 phenotype, which produces nitric oxide synthase, reactive oxygen species, interleukin-1 β (IL-1β), and tumor necrosis factor-alpha (TNF-α) to defend against infection." (PMID 36838330, 2023). "All septic animals showed reduced WBC counts as early as 2 h after infection compared to the preoperative concentrations, as well as increased serum concentrations of interleukin-6 (IL-6) and tumor necrosis factor-alpha (TNF-α)." (PMID 37371588, 2023). "Upon infection, TNF-α levels are increased both in serum and saliva, indicating an active state of immune responsiveness." (PMID 37629104, 2023). "After infection with B. abortus, the level of TNF-α will continue to increase, leading to the production of IL-12 and IFN-γ." (PMID 36911199, 2023). "Upon infection, the immune system triggers the release of proinflammatory cytokines, such as tumor necrosis factor-alpha (TNF-α), interleukin-1 (IL-1), and interferon-gamma (IFN-γ), which are intended to suppress parasite growth and proliferation." (PMID 37670044, 2023). "While cytokines such as TNF-α and IL-1 are important for protection against infection, excessive or insufficient cytokine production can result in diseases." (PMID 37998345, 2023). "We found that PRV-infection induced significantly higher transcriptional levels of TNF-α, IL-1β and IL-6, and that DMY-treatment exhibited significantly lower mRNA levels of these cytokines." (PMID 36851415, 2023). "The inflammatory response of the body after infection requires the initiation of the NF-κB signaling pathway, and the inflammatory factors TNF-α and IL-1β activate NF-κB, which regulates the production of the Bcl-2 anti-apoptotic protein." (PMID 37570890, 2023). "The rate of seropositivity was compared for patients with an in infection in the six months before serum sample collection and an infection more than six months before serum sample collection, for patients on anti-TNF, other ISPs and controls." (PMID 37198536, 2023). "Another study included persons with IBD ≥65 years, those on vedolizumab had a lower rate of infection-related hospitalizations (aHR: 0.47; 95% CI: 0.25, 0.86), compared to those on anti-TNF therapies." (PMID 37674503, 2023). "Meanwhile, SE infection also induced intestinal inflammation by upregulating inflammatory-related cytokine TNF-α mRNA levels, pro-inflammatory cytokines IL-1β and NF-κB mRNA levels in the ileum at the early infection stage." (PMID 37391807, 2023). "Breakthrough infection is more common in patients with IBD receiving the anti-TNF therapy infliximab compared with the gut-selective anti-integrin therapy vedolizumab." (PMID 37842172, 2023). "The results revealed that the release of IL-6 and TNF-α in sera following 2308ΔotnK and 2308ΔeryAΔotnK infection was significantly reduced relative to that found following infection with strain 2308." (PMID 37671873, 2023).
infection (continued). "MPOX inhibits chemokine receptor expression within the first week of infection, which is crucial for NK cell motility, cytotoxicity, and the release of TNF-α and IFN-γ, all of which contribute to the efficacy of NK cell-mediated clearance." (PMID 37533932, 2023). "Then, A3A-KO Calu-3 (clone #15) cells were infected with SARS-CoV-2 and were left untreated (control) or treated with IFN-ß and TNF-α before or after infection, similar to the treatment scheme for Calu-3 WT cells." (PMID 36610792, 2023). "By day 2 after infection, significant elevations in the levels of interleukin-1β (IL-1β), TNF-α, IL-6, IFN-γ, IFNα, IFNβ, CXCL1, CCL2, and CCL5 were detected in the airways of influenza virus–infected mice." (PMID 37683004, 2023). "TNFα can be explored for clinical application as administration of TNFα in wild-type and neutropenic mice showed protection against infection of A. fumigatus." (PMID 38143753, 2023). "In neonatal mice, inflammatory Ly6C+ monocytes recruited into the subepithelial intestine and macrophages are shifted to a proinflammatory phenotype during infection, produce TNF-α and IL-1β." (PMID 37325809, 2023). "In this regard, we found that blocking TLR-2 or -4 prior to infection with M. tuberculosis decreased the production of TNF-α and IL-6." (PMID 36863206, 2023). "After infection with the influenza virus, the expression of tumor necrosis factor (TNF)-α increased in the lungs of the H5N1+Lac− group, but there was no statistical significance compared with the H5N1−Lac− group (p = 0.2732)." (PMID 37571299, 2023). "Infection of monocytes by B19 results in decreased expression of tumor necrosis factor (TNF)-α mRNA." (PMID 37749597, 2023). "CRP has served as a useful marker of infection and tissue inflammation for several decades, and has been shown to be regulated by the pro-inflammatory cytokines TNF-α and IL-6 in an in vitro study." (PMID 36936907, 2023). "The colonic cytokine contents were analyzed, and it was detected that CR infection promoted the pro-inflammatory factors IL-1β, TNF-α, IL-6, and IL-17A (p < 0.01), as well as the anti-inflammatory factors IL-4 (p > 0.05) and IL-10 (p < 0.01)." (PMID 37111225, 2023). "As expected, the intracellular levels of ROS were increased after infection (LPS-dependent) or inflammation (IL-1β/TNFα) stimuli." (PMID 37443798, 2023). "Mtb is prone to aggregation during growth, and infection with aggregated Mtb leads to early upregulation of pro-inflammatory genes and enhanced TNF-α signaling via the NF-κB pathway." (PMID 37818041, 2023). "A previous study found that cell wall-associated lipids of N. brasiliensis promoted IL-6 production by macrophages and inhibited TNF-α production by macrophages during infection." (PMID 36926518, 2023). "S2) and found that neutrophils were a predominant source of TNF among BM-derived immune cells (CD45+) in the skin on day 3 after infection." (PMID 37327341, 2023). "The infection with Mtb increases CD4+TNF-α+, CD4+IFN-γ+, and CD4+IL-17+ in the lymph nodes of rBCG-LTAK63 immunized animals, while in the lungs, there was a drastic difference in CD4+IFN-γ+, and CD4+IL-17+, when compared with BCG." (PMID 37520577, 2023). "In contrast, caspase-1 inhibition blunted the amplitude of the HIV-1 induced cytokine storm as VX-765 treated huNSG mice only upregulated significantly the levels of IP-10 and TNF-α after infection (p<0.05 and 0.05, respectively)." (PMID 36800238, 2023). "Meanwhile, IL-33 increases the proliferation of CD8+ T cells as well as the production of the type 1 cytokine IFN-γ and TNF-α during infection." (PMID 37153553, 2023). "Macrophages are critical sensor cells that detect infection and induce inflammatory responses by producing cytokines such as TNFα and IL-1β." (PMID 37819792, 2023).
infection (continued). "Effector CD8+ T cells secrete pro-inflammatory cytokines such as IFN-γ and tumor necrosis factor (TNF) to inhibit viral replication, and express various chemokines to attract other inflammatory cells to sites of infection." (PMID 37332039, 2023). "Anti-TNF therapies have precise contraindications, such as cardiac insufficiency (grade 3 or 4), active TB, or severe concomitant infections." (PMID 37443755, 2023). "At that time of infection, these cells were more numerous in the anti-TNF group than in the MTX-treated animals (p=0.029)." (PMID 38106411, 2023). "Particularly, patients under anti-TNF therapy exhibited significantly lower values compared to those under vedolizumab therapy and also had a higher incidence of breakthrough infections." (PMID 37766088, 2023). "This study would provide evidence of the changes in the proportions of T and B lymphocyte populations in cancer patients relative to the current infection state along with the proinflammatory cytokine profiles of IL-1, IL-6, and TNF-α." (PMID 37068081, 2023). "In this study, we found different signaling for cancer progression and invasion of human gastric organoids in response to recombinant HDGF and TNFα during the infection with H. pylori." (PMID 37047540, 2023). "Then, we tested the effect of OLE in CFBE cells co-treated with LPS from P. aeruginosa or IL-1β/TNFα for 4 h to mimic the infection or inflammatory milieu of CF airways." (PMID 37443798, 2023). "TNF plays a crucial role in controlling and containing intracellular pathogens, recruiting inflammatory cells to foci of infection, and stimulating granuloma formation and maintenance." (PMID 37153610, 2023). "Simultaneously, IL-10 treatment in the late stage of infection effectively mitigated the production of pro-inflammatory factors such as IL-6, INF-γ, and TNF-α at 72 h post-infection, which are consequences of the inflammatory response." (PMID 38035330, 2023). "RTS11 cells pre-treated with CgPACAP-38 and infected with F. psychrophilum produced a significant up-regulation of IL-1β at day 3 after infection, while IL-6 and TNF-α were up-regulated from day 1 post-infection." (PMID 37887185, 2023). "A considerable elevation in IL-6 and TNF-α indicated the mice’s evident systemic inflammatory response to the E. papillata-induced infection." (PMID 36875142, 2023). "In this sense, IFN-γ and TNF also elevated in women with GT to control T. gondii in the initial phase of infection, but partial regulation is also crucial to ensure fetus protection." (PMID 36742306, 2023). "As a result, more T. marneffei were detected in TUT1-overexpressing THP-1 macrophages at 24 h post-infection, and pro-inflammatory factors (TNF-α, IL-1β) were down-regulated at 24 h post-infection." (PMID 37845378, 2023). "In a previous study, we found increased levels of IFN-γ, TNF-α, IL-17, and IL-1β in the spleens of μMT mice at two weeks post-infection." (PMID 37721965, 2023). "Following infection with T. congolense parasites in mice, C.f/L-extract administration increased production of IL-12p40, IL-6, TNF-α, and NO in macrophages." (PMID 37954253, 2023). "Using commercial ELISA kits, levels of IL-1β and TNF were also evaluated in serum samples taken from euthanized pigs at different days after infection." (PMID 36680273, 2023). "During the inflammatory phase of wound healing, macrophages have the ability to impede infection by discharging proinflammatory cytokines, namely IL-6, tumor necrosis factor (TNF)-α, and IL-1β." (PMID 37691943, 2023). "For the anti-F1 mAbs, protective efficacy appeared to be associated with downregulation of G-CSF, TNF-α and MIP-2 at 2 h post-infection." (PMID 37289480, 2023). "The release of four key mediators (MCP-1, TNF, IL-10, and IL-6) into the supernatant of cell cultures was measured before and after infection with BCG or stimulation with MDP." (PMID 36972292, 2023).
infection (continued). "In hyper-susceptible I/St mice, B-cell content markedly drops between weeks 12–16 post-infection, paralleled by diffuse lung tissue inflammation and elevated gene expression levels for pro-inflammatory cytokines IL-1, IL-11, IL-17a, and TNF-α." (PMID 36674664, 2023). "Specifically, we used priming of macrophages with recombinant TNF prior to infection in order to mimic the kinetics of initially infected cells inducing TNF production in uninfected neighboring cells to defend against the second wave of infection." (PMID 37279255, 2023). "Since bacterial infection of the mesothelium is characterized by a production of pro-inflammatory cytokines and an influx of innate immune cells to the site of infection, we assessed the levels of pro-inflammatory cytokines TNFα, IL-1β, and MCP-1." (PMID 37237611, 2023). "While in wild-type animals P. chabaudi is a mild infection, in this genetic background, P. chabaudi infection leads to lethal neuroinflammation dependent on TNF signaling for mortality." (PMID 38115011, 2023). "To determine if PAM-Tang cells exposed to S. suis have the ability to secrete pro-inflammatory cytokines, we used ELISA kits to detect the pro-inflammatory cytokines IL-18, IL-1β, and TNF-α secreted by PAM-Tang cells at different times post-infection." (PMID 36677452, 2023). "TNFα stimulated IL-8 production in a concentration-dependent manner, comparable to the effect elicited by the 24 h PA infection." (PMID 37432929, 2023). "We scored for IFN-γ, IL-12 p70, IL-1 β, TNF-α, IL-10, and IL-4 in their culture supernatants upon infection." (PMID 37928551, 2023). "Resolved mice are resistant to rUTI, in part because they have an accelerated, transient bladder TNFα/cyclooxygenase-2 (Cox-2) response, which promotes rapid elimination of infection and mucosal healing." (PMID 37037942, 2023). "In the HLN of primoinfected sheep, Th1 related cytokines (IL-1β and TNF-α) were overexpressed at early stages of infection, while in reinfected sheep these two cytokines were highly expressed in late stages." (PMID 36627694, 2023). "infection upregulates the expression of the pro-inflammatory cytokines (TNF-α, IL-1β, and IL-6) of the innate immune system and APCs, which express the secretion of RANKL." (PMID 37889704, 2023). "Our study revealed top 8 cytokines (IL-17, IL-1α, IL-2, IL-10, IL-5, IFN-γ, TNF-α and IL-6) and their biomarker abilities to discriminate different stages of infection." (PMID 36646786, 2023). "In human macrophages, we observed that the infection induced a strong upregulation of TNFα and a slight upregulation of IL-10 at 4 h post-infection independent of the availability of oxygen." (PMID 36793725, 2023). "Host cell infection following MAP infiltration caused an increase in the secretion of proinflammatory cytokines, such as IFN-γ, TNF-α, and IL-1β, through the upregulation of pathways related to the immune response in the MLN of the IP group at 6 weeks PI." (PMID 36795721, 2023). "TNF production was synergistically enhanced after LPS exposure in mice infected with Plasmodium yoelii, similarly to what was previously reported after infection with LDV, adenovirus, LCMV and Plasmodium chabaudi." (PMID 37240201, 2023). "When neutrophils before infection were preincubated with pGSN, a significant decrease in IL-4, IL-6, and TNF-α secretion was observed." (PMID 36802172, 2023). "The pro-inflammatory markers profile (CRP, IL1, IL6 and TNFα) was generally abnormal in the infection group in week 0 and those values seemed to improve throughout the weeks." (PMID 37762523, 2023). "Prior to infection, the disease protective latent condition presented the cytokine panel with mild or moderate levels of TNF-α, IFN-γ, IL-2, IL-17, and IL-6." (PMID 36646786, 2023). "We next compared the inflammatory response initiated after BMDM infection and observed that, similarly to in vivo results, TNFα and IL1β production was lower in Tirap+/- and Tirap-/- macrophages compared to infected WT cells." (PMID 36888688, 2023).